MMP9 (matrix metallopeptidase 9)
Diseases named in the same sentence as MMP9 in open-access papers (continued):
Sharing a sentence is not in itself a finding about the gene and the disease.
cancer (continued). "For example, Pai1 is induced by TGF-β in muscle satellite cells and MMP9 is an important Smad3 target in the process of cancer cell invasion." (PMID 21949838, 2011). "No prior study has shown an effect of HMGB1 on MMP-2 and TIMP-3 whereas it has been recently reported that HMGB1 enhances MMP-9 expression in neurons, via Toll-Like Receptor 4 signaling, and in cancer cells via NF-κB signalling." (PMID 21731608, 2011). "We conjecture that the enhancement of Snail expression by TG2 induces the acquisition in A431-III cells of a mesenchymal-like phenotype that then promotes the secretion of MMP-9, which enhances cancer cell motility and increases metastatic potential." (PMID 21777419, 2011). "Consistent with our findings, it was reported that up-regulation of actin and collagen with simultaneous down-regulation of MMP3 and MMP9 occurs as a measure to prevent the cancer formation in experimentally-treated mice." (PMID 21533263, 2011). "MMP-2 and MMP-9 plasma levels have been reported to be elevated in patients with various types of cancer." (PMID 21726449, 2011). "This in turn promotes MMP-9 activity, which increases cancer cell motility and metastatic potential." (PMID 21777419, 2011). "Among these both, the MMP-2 and MMP-9 contribute much more to the cancer invasiveness and metastasis." (PMID 21799674, 2011). "It caused significant inhibition in the production and secretion of MMP-2 and MMP-9 by activated monocytes and cancer cells by inhibiting the pro-inflammatory transcription factors NFκB and AP-1." (PMID 21349163, 2011). "MT1-MMP, MMP-2 and MMP-9, which are abundantly expressed in various malignant tumors, contribute to cancer invasion and metastasis." (PMID 21943213, 2011). "The percentage of fibroblasts that were positive for MMP-9 staining was lower than the percentage that were positive for MMP-2 in carcinomas." (PMID 21726449, 2011). "High level expression of MMP-2 and MMP-9 has been frequently correlated with increased tumor invasion and poor prognosis in various types of human cancer." (PMID 21151448, 2010). "Among them, MMP-2 and MMP-9 are known to be strongly correlated with the metastatic potential of cancer cells and in particular are prognostic factors in many solid tumors." (PMID 20169190, 2010). "Expression of MMP-2, MMP-9 and TNF-α is strongly linked with malignant tumor progression, angiogenesis and metastasis of various types of cancers." (PMID 20573279, 2010). "In epithelial ovarian cancer, the higher the amount of MMP9 positive cancer cells, the longer was the 10-year disease-related survival (DRS)." (PMID 20534121, 2010). "MMP-2 and MMP-9 play very critical roles in cancer, infectious disease, wound healing, inflammation and many vascular diseases." (PMID 21106094, 2010). "MMP-9, an enzyme that when secreted digests extracellular matrix to aid in invasion and metastasis typical of cancer cells, including those produced by arsenic, showed marked increases between 16 and 18 weeks of arsenic exposure in WPE-stem cells." (PMID 20056578, 2010). "The astrocytic MMP-9 factor can influence cancer cell invasion by promoting growth and angiogenesis in primary brain tumors through release of vascular endothelial growth factors (VEGFs) from the extracellular matrix." (PMID 21253507, 2010). "We examined the cytokines secreted by MDA-MB-231 cells in culture supernatants involving IL-6, TGF-β, VEGF and MMP9 which are required for cancer cellular invasion and metastasis." (PMID 20520770, 2010). "Consistent astrocyte activation was detected throughout the extravasation process as well as upregulation of matrix metalloproteinase-9 (MMP-9) proteins in close proximity of extravasating cancer cells." (PMID 21253507, 2010). "By inhibiting plasmin, TFPI-2 effectively decreases the activation of MMP-1, MMP-3 and MMP-9 and reduces the invasive potential of several cancer cell lines." (PMID 21062455, 2010).
cancer (continued). "Recent evidence suggests that neutrophil gelatinase-associated lipocalin (NGAL) expression is induced in many types of human cancer, while detection of its complex with matrix metalloproteinase-9 (MMP-9) is correlated with cancer disease status." (PMID 19889214, 2009). "Matrix metalloproteinase-9 (MMP9) has been implicated in numerous somatic illnesses, including cardiovascular disorders and cancer." (PMID 20037727, 2009). "Intriguingly, hypoxia has been shown to upregulate gelatinases (MMP-2 and MMP-9), and to enhance cancer cell invasiveness in vitro." (PMID 19426483, 2009). "MMP-9 are metalloproteases that have been shown to participate in cancer pathogenesis as they degrade type IV collagen, a major component of basement membrane, as well as other types of collagens (V, VII and X), elastin and fibronectin." (PMID 19789535, 2009). "Five markers increased in cancer patients by 39–246%: carbonyls, lactate dehydrogenase, metalloproteinase-9 (MMP-9), Ki67 and Cyclin D1 (CycD1) (P⩽0.01)." (PMID 19789535, 2009). "Several lines of evidence in vitro or in vivo have suggested that NGAL plays an important role in the enhanced invasive potential of cancer cells by upregulating MMP-9 expression." (PMID 19419554, 2009). "Five of these were increased in the cancer patients by 39–246%: carbonyls, Ki67, CycD1, MMP-9 and LDH (P⩽0.01)." (PMID 19789535, 2009). "We also measured the effect on the expression of CD44v6, VEGF-C, and MMP-9 which were related to cancer and/or metastasis." (PMID 19804631, 2009). "Compared with cancer-free controls, increased MMP-9, DJ-1 and A1BG expression in cancerous pancreatic juice were detected by Western blot." (PMID 18706098, 2008). "Invasion of cancer cell induced by matrix metalloproteinase-9 (MMP-9) is one of pivotal steps in cancer metastasis." (PMID 19052522, 2008). "By contrast, it appeared that subjects with positive immunostaining for MMP-2, -8, -9, or -28 in the cancer cells or MMP-9 or ER-β in inflammatory cells would have a better prognosis than other patients." (PMID 18253113, 2008). "Inflammation in cancer, particularly macrophage infiltration and MMP-9 release, generates a microenvironment advantageous to neoplastic progression, with recent evidence indicating that a PMN source of MMP-9 can also promote tumorigenesis." (PMID 17375198, 2007). "Expression of OPG/RANK/RANKL in cancer cells has been suggested to have a role in the expression and activity of MMP-9 as well as cancer metastasis." (PMID 17343740, 2007). "Further evidence supports an important role for c-Src in modulating expression of MMP-9, in particular, in human cancer cells." (PMID 15316565, 2004). "We also demonstrated that the incubation of monocytes with MDA-MB231 cancer cells induced an increase in MMP-9 secretion." (PMID 12698185, 2003). "As for u-PA, an increased secretion of MMP-9 is proposed to be involved in cancer invasion and metastasis." (PMID 12698185, 2003). "Poorly differentiated SCC had more MMP-9 expression than moderately and well differentiated carcinomas (P=0.003)." (PMID 14647147, 2003). "Expression of MMP-9 was observed in the cytoplasm of carcinoma cells, stromal fibroblasts and vascular endothelial cells." (PMID 14647147, 2003). "Matrix metalloprotease-9 (MMP-9; 92 kDa type IV collaganase, gelatinase B) is regarded as, important for degradation of the basement membrane and extracellular matrix during cancer invasion and other tissue-remodelling events." (PMID 11384099, 2001). "MMP-9 staining was observed primarily in cancer cells, and to a lesser degree in surrounding stromal cells." (PMID 11384099, 2001). "The system was functionalized with two different anticancer drugs, doxorubicin or pemetrexed, using an on-demand release strategy based on a proteolytic sequence specifically recognized by metalloproteinase-9 (MMP-9), an enzyme overexpressed in various cancers." (PMID 42205116, 2026).
cancer (continued). "Succinylated gelatin enabled the electrostatic conjugation of DOX with gadolinium oxide nanoparticles, and the release of DOX was controlled through the enzymatic degradation of gelatin by matrix metalloproteinases-2 and -9 (MMP-2 and MMP-9), which are highly expressed in cancer cells." (PMID 41893218, 2026). "PDA exposure also induced epithelial–mesenchymal transition (EMT), upregulated cancer stem cell markers (CD44, CD117, CD133, Sox2, Oct4, and Nanog), and elevated expression of metastasis- and chemoresistance-associated molecules (MMP-2, MMP-9, MDR1, and MRP1)." (PMID 41596307, 2026). "Elevated levels of MMP‐2 and MMP‐9 are often observed in various cancers." (PMID 41546170, 2026). "Among the MMP family, MMP-2 and MMP-9 are particularly significant in cancer progression." (PMID 40563423, 2025). "Moreover, several regulator proteins, growth factors, and cytokines, like IFN-γ, EGF, and TNF, exert their oncogenic effect by upregulating MMP-9,30, 31, 32, 33 suggesting its central role in cancer progression." (PMID 41273852, 2025). "MMP‐9 is instead a tricky enzyme; in fact, its inhibition might be useful in patients with early‐stage cancers, but it is an anti‐target in patients with advanced disease." (PMID 40556034, 2025). "Since the overexpression and dysregulation of MMP-9 levels are associated with various diseases, the regulation and inhibition of MMP-9 is an important therapeutic approach for combating various diseases including cancer." (PMID 40565127, 2025). "Moreover, unlike free BrP, NF andNF-BrP did not impair mitochondrial respiration and showed no effecton ROS production, suggesting that BrP toxicity requires release,likely via MMP-9 cleavage in cancer cells." (PMID 41124053, 2025). "While quercetin is often reported to downregulate MMP9 in various cancer models, this study demonstrated that under certain inflammatory conditions, quercetin might have an opposite effect." (PMID 40566630, 2025). "This may be due to increased expression of immune checkpoint inhibitors such as CD47 (cluster of differentiation 47, which inhibits phagocytosis and cytotoxicity of phagocytes on host and cancer cells) and matrix metalloproteinase 9 (MMP-9)." (PMID 41011327, 2025). "MMP-9 exceeded the highest standard value in 2% (2/54) of cancer subjects and 0% of controls." (PMID 40722499, 2025). "Some MMP9 inhibitors have undergone testing in various cancers during phase I–III clinical trials." (PMID 40259907, 2025). "Additionally, in BC, ERβ enhances the invasive ability of cancer cells by influencing MMP9 expression." (PMID 40007149, 2025). "Several cancers, such as hepatocellular carcinoma, prostate cancer, and head and neck squamous cell carcinomas, have exhibited altered apoptosis resistance and invasion through the regulation of MMP9-related signalling pathways." (PMID 40830065, 2025). "Thus, the mounting evidence points to MMP-9’s critical involvement in GB pathophysiology, making it a key focus in ongoing cancer research and therapeutic development." (PMID 41154699, 2025). "Collectively, our results demonstrate that structure and bioactivity‐guided synthesized new compounds intersect at the VDAC1/PHB/MMP9 crossroads and exhibit cancer‐specific cytotoxic properties, inducing apoptosis and suppressing the energy metabolism and stemness of CRC." (PMID 41179704, 2025). "Given that M2 macrophages are known to induce epithelial‐mesenchymal transformation (EMT) in cancer cells, we explored the correlation between VSIG4 and several biomarkers associated with EMT processes (MMP9, SNAI1, SNAI2, VIM, TWIST1, TWIST2, CDH1, CDH2) in CRC through the TIMER2.0 website." (PMID 40405491, 2025).
cancer (continued). "Moreover, it was observed that CARHSP1 increased the expression of MMP2 and MMP9 at the mRNA level and the protein level, which play vital roles in tissue remodeling, cancer progression, and metastasis." (PMID 40055805, 2025). "The modulation of pathways involved in cancer metastasis (MMP9), inflammation (PTGS2), cell survival (AKT1), and DNA repair (PARP1) suggests that these compounds could serve as multitargeted therapies, providing an advantage over single-target drugs." (PMID 40283891, 2025). "Furthermore, the pro-tumor factors secreted by M2 macrophages (such as VEGF and IL-6) promote cancer cell proliferation while assisting cancer cells in invading and metastasizing by remodeling the extracellular matrix (such as by secreting MMP-9)." (PMID 40109347, 2025). "Several studies have shown that MMP9 is a mediator of cancer metastasis." (PMID 39990676, 2025). "Therefore, future efforts should focus on characterizing cancer-specific MMP9 glycoforms to enhance specificity and clinical relevance." (PMID 41041068, 2025). "Metalloproteinases (MMP-2 and MMP-9) are involved in the destruction of the extracellular matrix, and their increased expression may increase the migration and invasive potential of cancer cells." (PMID 39352533, 2025). "Research suggests that implementing a KD alongside traditional cancer treatments may significantly inhibit MMP-9 expression in mouse models of colon cancer." (PMID 41398969, 2025). "Moreover, OPN upregulates CD44 and MMP-9 expression, providing a more potent ability for cancer cell invasion and metastasis development." (PMID 39941741, 2025). "Inhibition of MMP2 and MMP9 has been shown to alleviate cancer progression." (PMID 39895792, 2025). "Furthermore, CXCL8 can regulate the activity of MMPs, such as MMP-2 and MMP-9, which degrade the extracellular matrix, allowing cancer cells to invade neighboring tissues." (PMID 40362280, 2025). "Additionally, hypoxic CAF-derived exosomes increase MMP-9 and IL-8 expression, enhancing cancer cell invasion via GPR64, with BNIP3 phosphorylation regulating the process." (PMID 40230452, 2025). "Furthermore, in a c-Met-overexpressing individual-derived xenograft model, luteolin significantly suppressed the growth of cancer and decreased the expression of c-Met, ki-67, and MMP-9 in malignant tissues." (PMID 40427522, 2025). "Moreover, glucose starvation induces cancer cell migration in processes involving the upregulation of MMP9, whose activation depends on NRF2." (PMID 40278372, 2025). "Additionally, serum levels of the MMP-9/NGAL complex were significantly elevated in UADT cancer patients relative to controls." (PMID 40214460, 2025). "Additionally, this signaling pathway has been identified as a mediator of the enhanced migration and invasion of cancer cells through the stimulation of matrix metalloproteinase-9 (MMP-9) production." (PMID 40214484, 2025). "To support the gene expression results, we performed protein expression analysis of the key proteins associated with cancer progression, including MMP2 and MMP9, which are involved in ECM degradation, and N-cadherin, which plays an important role in cancer cell invasion and metastasis." (PMID 41226554, 2025). "Rutin significantly inhibited the migration and invasion of TNBC cells, which may be attributed to its downregulation of matrix metalloproteinases (MMPs) such as MMP-2 and MMP-9, proteins crucial for cancer metastasis." (PMID 39802656, 2025). "Increased MMP-2 and MMP-9 expression has also been reported to correlate with cancer invasion." (PMID 39941886, 2025). "qPCR analyses revealed that RLN2-secreting CAR-T cells, particularly activated cells, induced MMP-2 and MMP-9 expression, though at lower levels than that in cancer cells, suggesting that the primary mechanism of stromal dissolution by RLN2-secreting CAR-T cells is paracrine, acting on cancer cells." (PMID 40666525, 2025).
cancer (continued). "Furthermore, eupatilin markedly decreased both the mRNA expression and enzymatic activities of matrix metalloproteinases (MMP)-2 and MMP-9, indicating its potential to inhibit cancer cell invasion." (PMID 41471692, 2025). "In addition, KEGG pathway enrichment analysis identified pathological conditions related to cancer, endocrine disorder, infection, and relaxin signaling, characterized by increased MMP9 level." (PMID 39562369, 2025). "Our characterization of this hotspot mutation, leveraging primary human keratinocytes and the Ras-CDK4 cSCC model, demonstrates that the SRCAP-1879 truncation is sufficient to dysregulate gene expression in a cell-state-dependent manner and promote cancer invasion with the induction of MMP9." (PMID 40858549, 2025). "Furthermore, the expression of MMP‐9, an enzyme functioning in cancer invasion was also investigated." (PMID 39980332, 2025). "MMP9, a gene integral to extracellular matrix disintegration and cancer spread, is modulated by many transcription factors and may be meticulously regulated throughout cellular migration and tissue remodelling." (PMID 40475773, 2025). "HCC patients with increased numbers of cancer stem cells also displayed an accumulation of a HIF-1α-driven SPP1+ macrophage subset characterized by the expression of MMPs (MMP9, MMP12, and MMP17), which may enhance cancer epithelial‒mesenchymal transition." (PMID 40721870, 2025). "The activity of matrix metalloproteinase-9 (MMP-9) is known to be involved in the degradation of the extracellular matrix and basement membrane, and its elevated levels have been associated with cancer progression and reduced patient survival." (PMID 41150756, 2025). "The observed anticancer polarization of these cancer-associated fibroblasts in response to treatment may be related to a reduction in CCL2, TNC, MMP9 and MMP-2." (PMID 41009006, 2025). "Reports indicate that MMP-9 is also involved in cancer pathogenesis." (PMID 40869267, 2025). "Hence, in the present study, cell proliferation, cell cycle, apoptosis, migration, and invasion were also selected as indicators to observe the functional changes of cancer cells in the case of circDENND4C, miR-200b, and MMP-9 overexpression and knockdown." (PMID 40034591, 2025). "Simultaneously, activation of the small GTPase Ras plays a critical role in stabilizing HIF-1α, a transcription factor that promotes the expression of MMP-9 and fascin—a protein that bundles actin filaments and enhances cancer cell migration, dispersion, and invasion." (PMID 40322886, 2025). "Furthermore, EGCG suppresses the activity of matrix metalloproteinases (MMP-2 or MMP-9), enzymes responsible for extracellular matrix degradation, thereby limiting cancer cell proliferation and invasion." (PMID 40667502, 2025). "MMP-9 facilitates cancer cell invasion and metastatic progression." (PMID 40149289, 2025). "However, the literature confirms that MMP-2 and MMP-9 are often co-released into the extracellular matrix during inflammation, fibrosis, and cancer progression, supporting the need for multiplex biosensing." (PMID 41002342, 2025). "ATRA is the major biologically active form of vitamin A and may selectively regulate the expression and activity of matrix metalloproteinases (MMPs), such as MMP-2 and MMP-9, in cancer progression and metastasis." (PMID 38732186, 2024). "Additionally, the interaction of Ox-LDL with LOX-1 activates NF-κB target genes like VEGF, MMP-2, and MMP-9 to encourage the growth, invasion, and angiogenesis of cancer cells." (PMID 39290325, 2024). "Given the critical roles of MMPs and TIMPs in cancer biology, we hypothesized that MMP-9, MMP-14, TIMP-1, and MMP-2 could serve as prognostic biomarkers for regorafenib efficacy in mCRC patients." (PMID 39199626, 2024). "Elevated levels of MMPs, particularly MMP-2 and MMP-9, often correlate with increased chemokine levels, reflecting a complex interplay between these proteases and chemokine signaling in cancer." (PMID 39409924, 2024).